SLC16A1 (solute carrier family 16 member 1)
Diseases named in the same sentence as SLC16A1 in open-access papers (continued):
Sharing a sentence is not in itself a finding about the gene and the disease.
metabolic disease (2 papers, 2021 to 2025). A congenital disorder (due to inherited enzyme abnormality) or acquired (due to failure of a metabolically important organ) disorder resulting from an abnormal metabolic process. "In the context of UC, downregulated SLC16A1 expression may lead to lactate metabolism disorders, which not only affects energy supply and mucosal regeneration in intestinal epithelial cells but may also indirectly impact centrosome function through disruption of cellular metabolic homeostasis." (PMID 41459538, 2025). "There are several advantages of SLC16A13/MCT13 over MCT1 in terms of a pharmacological target for the treatment of metabolic disease: First, homozygous deletion in mice leads to viable offspring, which is not the case in Slc16a1 knockout mice." (PMID 34211098, 2021).
hematological cancer (1 paper, 2021). "Analysis of SLC16A1/SLC16A3 expression ratio in 205 hematological cancer cell lines, identified 44 cell lines, primarily of lymphoid origin, that are predicted to be sensitive to AZD3965." (PMID 34907165, 2021).
hematological malignancies (1 paper, 2021). "Our findings show that the combined expression of SLC16A1 (high) and SLC16A3 (low/no) may serve as an actionable biomarker for AZD3965 response in hematological malignancies." (PMID 34907165, 2021).
mitochondrial disease (1 paper, 2019). "For example, in patients Pt11 and Pt22, who met the criteria for mitochondrial disease with relatively high MDC scores, DNA analysis identified biallelic changes in NPHS2 and SLC16A1, which might be a phenocopy of mitochondrial disease." (PMID 31683770, 2019).
urinary diseases (1 paper, 2021). "It is also shown that in comparison with the corresponding normal tissues, SLC16A1 was upregulated in the urinary diseases." (PMID 34631536, 2021).
SLC16A1 also shares sentences with these, for which no sentence is quoted: hepatocellular carcinoma (6 papers); colorectal cancer (3); head and neck squamous cell carcinoma (3); Hyperinsulinemia (3); non-small cell lung carcinoma (3); pancreatic ductal adenocarcinoma (3); acute myeloid leukemia (2); adenoma (2); Alzheimer disease (2); Cerebral ischemia (2); diffuse large B-cell lymphoma (2); head and neck cancer (2); hyperinsulinemic hypoglycemia (2); ischemia (2); lung carcinoma (2); sarcoma (2); ulcerative colitis (2); alopecia (1); Arthritis (1); autism spectrum disorder (1); autoimmune hepatitis (1); colitis (1); colorectal tumour (1); diabetic nephropathy (1); endometrial cancer (1); esophageal cancer (1); female reproductive cancer (1); head and neck tumors (1); Hepatic steatosis (1); hepatitis C (1).
A further 23 diseases each share a sentence with SLC16A1 in 1 paper.